EDN1 (endothelin 1)
Diseases named in the same sentence as EDN1 in open-access papers (continued):
Sharing a sentence is not in itself a finding about the gene and the disease.
congenital heart disease (4 papers, 2014 to 2024). A heart disease that is present at birth. "A complementary analysis was performed to explain the behavior of endothelial and progenitor cells from the initial mechanism of congenital heart disease and the effect of the surgical procedure, identifying the value of endothelin-1 as the only related variable." (PMID 39201580, 2024). "The results highlight the potential role of 5′UTR of edn-1 gene in modulating the expression of ET-1 in CHD patients under study, by unknown mechanisms, which in turn may alter the course of congenital heart anomaly after it has been initiated." (PMID 34011397, 2021).
Headache (4 papers, 2019 to 2024). Cephalgia, or pain sensed in various parts of the head, not confined to the area of distribution of any nerve. "Clinical efficacy, headache score, headache attack frequency, duration of each attack, TCM syndrome score, Pittsburgh Sleep Quality Index score, and serum biochemical indicators (5-hydroxytryptamine [5-HT] and endothelin-1 [ET-1]) were compared between the 2 groups before and after treatment." (PMID 39213252, 2024).
hepatopulmonary syndrome (4 papers, 2007 to 2025). Hepatopulmonary syndrome (HPS) is a lung disease characterized by widening of arteries and veins (dilatation) in the lungs in people who have chronic liver disease. "High levels of endothelin-1 are associated with the development of hepatopulmonary syndrome." (PMID 38396668, 2024). "Another vasoactive substance secreted by proliferating BECs is endothelin-1 (ET-1), which is involved in the regulation of vascular bed function and plays an epicenter role in experimental hepatopulmonary syndrome after BDL." (PMID 35941604, 2022). "However, exogenous administration of endothelin-1 to partial portal vein ligated rats increased TNF-α levels, increased pulmonary cNOS production and pulmonary intravascular macrophage accumulation, and led to the development of hepatopulmonary syndrome." (PMID 17999758, 2007).
hypercoagulability (4 papers, 2021 to 2025). "These autoantibodies induce vasoconstriction via endothelin-1 (ET-1) activation, necrosis and apoptosis of umbilical vein endothelial cells, reduced trophoblast invasion, and increased reactive oxygen species (ROS) production, which stimulates tissue factors and leads to hypercoagulability." (PMID 41303027, 2025).
hyperhomocysteinemia (4 papers, 2010 to 2021). A serious metabolic condition caused by mutations in the MTHFR gene, medications, or nutritional deficiency. "For the underlying mechanism of transition process, previous studies have revealed the roles of TGFβ, hypoxia, angiotension II, endothelin-1, IL-6, hyperhomocysteinemia (HHcy), cylindromatosis (CYLD), nicotinamide adenine dinucleotide phosphate (NADPH) oxidase 4 (Nox4), and Fizzl." (PMID 34901214, 2021).
hyperphosphatemia (4 papers, 2017 to 2023). Abnormally high level of phosphate in the blood. "Additional investigations have indicated that hyperphosphatemia induces human EC senescence by increasing endothelin-1 production and that HVEC senescence promotes endothelin-1 expression." (PMID 37199574, 2023). "Hyperphosphatemia leads to vascular dysfunction through endothelin 1 and NO imbalances." (PMID 35928251, 2022). "Hyperphosphatemia impairs endothelial cell function through endothelin-1 and NO imbalances leading to dysfunction of the endothelium, an important step in the pathogenesis of atherosclerosis which can impair functionality of all the organs, including renal and cardiac functions." (PMID 35928251, 2022).
lymph node metastasis (4 papers, 2008 to 2023). "Herein, the expression of endothelin-1 (ET-1) in EBVaGC was lower than of Epstein-Barr virus-negative gastric carcinoma (EBVnGC) and associated with a low frequency of lymph node metastasis of EBVaGC." (PMID 36475746, 2023).
metastatic disease (4 papers, 2004 to 2019). "Increased endothelin-1 levels in blood cause inappropriate vasoconstriction, systemic hypoxic effects, and predisposition to aggressive metastatic disease." (PMID 31739537, 2019). "Endothelin-1, in particular, has been demonstrated in prostatic tissue in vivo and in human PC lines in vitro with plasma ET-1 concentrations significantly elevated in men with metastatic disease." (PMID 15083188, 2004). "FS generally affects young females demonstrating specific molecular patterns including endothelin-1 (ET-1) and activity of metalloproteinases MMP-9, MMP-2 characteristic for BC, and metastatic disease with poor prognosis." (PMID 31739537, 2019).
nasopharyngeal carcinoma (4 papers, 2014 to 2024). A carcinoma arising from the nasopharyngeal epithelium. "In human nasopharyngeal carcinoma, EZH2 inhibits miR-1 transcription via promoter binding activity, leading to enhanced expression of Endothelin-1 (ET-1) which is suppressed by miR-1 targeting of ET-1 3’UTR." (PMID 29221202, 2017).
ovarian tumor (4 papers, 2015 to 2016). "Endothelin-1 (ET-1) is a vasoconstrictor peptide that binds two G-protein-coupled transmembrane receptors (ETA and ETB) and has been implicated in EMT in ovarian tumors." (PMID 26356073, 2015).
Parkinsonism (4 papers, 2012 to 2025). Characteristic neurologic anomaly resulting from degeneration of dopamine-generating cells in the substantia nigra, a region of the midbrain, characterized clinically by shaking, rigidity, slowness of movement and difficulty with walking and gait. "Additionally, SNPs in the common genes encoding EDN1 and MYO5B have been associated with multiple systems atrophy (which presents with parkinsonism) and loss of the sense of smell (an early non-motor PD-symptom), respectively." (PMID 32858884, 2020).
renal cell carcinoma (4 papers, 2016 to 2025). "We noticed that several stress response genes such as Drr1 (down-regulated in renal cell carcinoma 1, also called family with sequence similarity 107 (Fam107A)), Edn1, Klf9, and Nfkbia39, 40, 41, 42 were significantly increased in Cpeb4GT/GT spinal cord, which was independently validated by RT-qPCR." (PMID 27381259, 2016).
Respiratory distress (4 papers, 2016 to 2022). Respiratory distress is objectively observable as the physical or emotional consequences from the experience of dyspnea. "The rs2070699 SNP of EDN1 has been suspected to be associated with neonatal respiratory distress and PPHN." (PMID 36620618, 2022). "Most recently, rs2070699 in endothelin 1 (EDN1) was found to increase the risk of PPHN with respiratory distress." (PMID 31382961, 2019). "In conclusion, this study provides the first evidence of an association between the EDN1 rs2070699 SNP and the risk of PPHN in Chinese neonates with respiratory distress." (PMID 27425626, 2016).
vitamin D deficiency (4 papers, 2018 to 2025). A nutritional condition produced by a deficiency of VITAMIN D in the diet, insufficient production of vitamin D in the skin, inadequate absorption of vitamin D from the diet, or abnormal conversion of vitamin D to its bioactive metabolites. "In another study, high blood leptin and endothelin-1 levels, vitamin D deficiency, and food reward hormone dysregulation were found in normal weight children exposed to high concentrations of ambient PM2.5 in Mexico City." (PMID 39767974, 2024). "In addition, it is thought that vitamin D deficiency may increase urine production by affecting the expression of renal factors such as endothelin-1." (PMID 40506917, 2025).
aortic aneurysm (3 papers, 2020 to 2023). A ruptured aneurysm located in the wall of the proximal portion of the descending aorta proceeding from the arch of the aorta. "Endothelin-1 overexpression induced aortic aneurysms in mice by increasing oxidative stress, inflammatory cell infiltration, and matrix metalloproteinase-2 in perivascular fat, vascular wall, and atherosclerotic lesions." (PMID 34912865, 2021).
bone metastasis (3 papers, 2015 to 2020). Transfer of a neoplasm from its primary site to bones. "However, for bone metastasis predictive value, the association of SPARC signal with those of Endothelin 1/ETAR seemed essential, starting from their presence in the dysplastic lesions." (PMID 26703564, 2015). "In conclusion, without associated strong SPARC expression, the Endothelin 1/ETAR positivity in dysplastic lesions did not appear to be sufficient as predictive index of bone metastasis." (PMID 26703564, 2015). "Concomitantly, the expression of Endothelin 1 and of its receptor ETAR were assayed to clarify whether the Endothelin 1/ETAR pattern completed SPARC findings as predictive value for bone metastasis." (PMID 26703564, 2015).
brain edema (3 papers, 2014 to 2020). Increased intracellular or extracellular fluid in brain tissue. "Additionally, it is noticeable that risk factors of cardiac remodeling, such as endothelin-1 and matrix metalloproteinase, are also associated with brain edema." (PMID 32993551, 2020).
cardiac arrest (3 papers, 2014 to 2021). Cessation of breathing and/or cardiac function. "Besides, endothelin-1 has been shown to be elevated in the post-arrest period in cardiac arrest patients and in the delayed hypoperfusion period after global cerebral ischemia in dogs." (PMID 24642693, 2014).
Crohn disease (3 papers, 2021 to 2024). A gastrointestinal disorder characterized by chronic inflammation involving all layers of the intestinal wall, noncaseating granulomas affecting the intestinal wall and regional lymph nodes, and transmural fibrosis. "High concentrations of endothelin-1 (EDN1) are present in the colonic tissue of mice with Crohn's disease and UC." (PMID 37016023, 2023). "In agreement with the findings of our study of patients with PC, elevated levels of EDN1 in the plasma have also been observed in patients with a number of chronic painful intestinal diseases including Crohn's disease and ulcerative colitis." (PMID 35295482, 2021).
demyelinating disease (3 papers, 2018 to 2025). A broad group of disorders that affect the myelin sheaths that cover the neurons. "In this study, the involvement of endothelin-1 in the development and progression of demyelinating diseases was investigated using these two experimental models." (PMID 33069239, 2020). "Although endothelin-1 level elevation was previously observed in the CNS of mice with EAE and viral demyelinating disease, the potential role of endothelin-1 in the development of these demyelinating diseases is unknown." (PMID 33069239, 2020).
Fever (3 papers, 2020 to 2022). Body temperature elevated above the normal range. "Moreover, called pathogenic fever, this model is triggered by increased prostaglandin E2 (PGE2) synthesis and release of the endogenous pyrogens IL-1β, IL-6, TNF-α, endothelin-1 (ET-1), corticotropin-releasing factor (CRF), bradykinin, and preformed pyrogenic factor (PFPF)." (PMID 37430944, 2022).
galactosialidosis (3 papers, 2014 to 2017). A lysosomal storage disease characterized by coarse facial features, macular ''cherry red spot'', and dysostosis multiplex. "Our immunohistochemistry results indicated that endothelin-1 accumulated in hippocampus of CathAS190A mice, consistent with the previously reported distribution of this peptide in the brain tissue of galactosialidosis patients and western blot analysis results derived from knockout animal models." (PMID 28133419, 2017). "Although, the markedly increased endothelin-1-specific immunoreactivity has been demonstrated in CTSA deficient galactosialidosis patient's brain, we did not observe any difference neither in brain nor in liver from CTSAS190A mice using ELISA." (PMID 27826550, 2016).
gastric ulcer (3 papers, 2020 to 2023). An ulcerated lesion in the mucosal surface of the stomach. "Endothelin-1 (EDN1) and Endothelin receptor type-A (ENDRA) were also found to be upregulated and EDN1 previously was shown to contribute to the pathogenesis of hemorrhagic shock resulting from gastric mucosal damage, analogous to gastric ulcer." (PMID 33276578, 2020).
gingival overgrowth (3 papers, 2013 to 2023). Excessive growth of the gingiva either by an increase in the size of the constituent cells (gingival hypertrophy) or by an increase in their number (gingival hyperplasia). "Among the various mast cell mediators and their roles in gingival overgrowth, the function of endothelin-1 (ET-1) is particularly intriguing." (PMID 23431239, 2013). "The expression of endothelin-1 has been shown in gingival fibroblasts, and several studies have demonstrated that its levels are higher in patients affected by periodontal diseases, inflammation, and gingival overgrowth." (PMID 36826858, 2023).
Hypoglycemia (3 papers, 2019 to 2025). A decreased concentration of glucose in the blood. "Hypoglycemia also induces the production of several inflammatory markers, including interleukin(lL)-6, C-reactive protein, TNFα, IL-8, and endothelin-1, which can cause endothelial injury." (PMID 30813549, 2019).
IgA nephropathy (3 papers, 2024 to 2025). "We found an association between eGFR and endocan, endothelin-1, and NT-proBNP in IgA nephropathy." (PMID 39408883, 2024). "The authors also found a statistically significant relationship between initial plasma endothelin 1 concentrations and total serum protein concentrations following 1 year of monitoring in the IgA nephropathy cohort (n = 16; p = 0.01; r = −0.61)." (PMID 41517469, 2025). "Initial plasma levels of endothelin 1 correlated negatively with creatinine after 1 year of monitoring in IgA nephropathy." (PMID 41517469, 2025). "Endothelin 1 correlated with albumin in membranous nephropathy, total protein, albumin, creatinine in FSGS, total protein in IgA nephropathy, total protein, and albumin in CKD." (PMID 41517469, 2025).
keloid (3 papers, 2022 to 2025). An irregularly shaped, elevated mark on the skin caused by deposits of excessive amounts of collagen during wound healing. "External dataset validation, qPCR, correlation analysis, HE staining, and IHC results demonstrated that EDN1 and NTF3 were highly expressed in keloid tissues and were associated with excessive collagen deposition and immune cell infiltration." (PMID 40051702, 2025). "As illustrated in the violin plots, EDN1 expression is notably higher in keloid tissues compared to normal skin, with the keloid group showing a marked increase in mRNA levels." (PMID 40051702, 2025). "In keloids, EDN1 likely exacerbates inflammatory responses and fibroblast overproliferation by promoting ROS generation and activating the MAPK signaling pathway, resulting in abnormal ECM deposition." (PMID 40051702, 2025). "In keloid tissues, EDN1 and NTF3 were significantly upregulated, accompanied by prominent fibrotic features such as thickened and disorganized collagen fibers." (PMID 40051702, 2025). "The qPCR analysis of NTF3 and EDN1 mRNA expression levels in normal skin and keloid tissue reveals a significant increase in both genes in keloid tissues." (PMID 40051702, 2025). "The immune cell infiltration and correlation analysis in keloid tissues revealed significant associations between the expression of the hub genes ADRB2, NTF3, VCAM1, EDN1 and various immune cell types." (PMID 40051702, 2025). "This study found that the abnormal overexpression of key genes, such as EDN1 and NTF3, in keloid tissues is closely associated with significant fibrotic and inflammatory phenotypes." (PMID 40051702, 2025). "Endothelin-1 (ET-1), a powerful vasoactive peptide responsible for regulating vascular tone and produced by ECs, was observed to be highly expressed in keloid." (PMID 37809065, 2023). "In contrast, keloid tissues exhibited significantly higher expression levels of both EDN1 and NTF3." (PMID 40051702, 2025). "In this study, EDN1 was positively correlated with activated mast cells, suggesting that EDN1 may promote mast cell activation, drive fibrosis progression in keloid tissues, and amplify inflammatory responses." (PMID 40051702, 2025). "In the violin plot, EDN1, NTF3, ADRB2, and VCAM1 were found to be significantly upregulated in keloid tissue, with very high statistical significance (***, p < 0.001)." (PMID 40051702, 2025). "Ultimately, 7 hub genes—EDN1, NTF3, VCAM1, ADRB2, BDNF, F3 and FLT1—were identified, all of which had interaction scores above 0.70, indicating their potential roles in keloid formation and progression." (PMID 40051702, 2025). "The ROC analysis revealed that EDN1 and NTF3 exhibited high sensitivity and specificity in distinguishing keloid tissues from normal tissues, highlighting their potential value as biomarkers." (PMID 40051702, 2025). "Additionally, EDN1 and NTF3 exhibited high correlations with fibrosis markers (COL1A1, TGFB1), inflammatory cytokines (IL6, TNFA), and immune cell infiltration (e.g., activated mast cells), suggesting their central regulatory roles in keloid-associated fibrosis and inflammation." (PMID 40051702, 2025). "As a result, EDN1 and NTF3 were identified as the most important hub genes, warranting further investigation into their roles in the formation and progression of keloids." (PMID 40051702, 2025). "In terms of expression level, BMP4, MSX1, TBX2, SIX1, DLX5, and DLX2 were lowly expressed, while HAND2, IRX1, EDN1, and MEF2C were highly expressed in keloid fibroblasts." (PMID 35047146, 2022). "At the transcriptome-wide level, this further suggests that EDN1 and NTF3 may play dual regulatory roles in the fibrosis and inflammation processes of keloids." (PMID 40051702, 2025). "EDN1 and NTF3, as OSRDEGs, play critical roles in the pathogenesis and progression of keloids." (PMID 40051702, 2025).
keloid (continued). "The heatmap illustrates the differential expression of these 13 OSRDEGs between keloid and normal skin tissues, where F3, FOXL2, EDN1, and NTF3 show higher expression in keloid tissues, while BDNF, FLT1, VCAM1 and ADRB2 are more highly expressed in normal skin." (PMID 40051702, 2025).
liver failure (3 papers, 2014 to 2020). A liver disease characterized by the liver losing or has lost all of its function. "Patients were divided into 2 groups (group A: LiMAx ≥100 μg/kg/h, moderate liver dysfunction; group B: LiMAx <100 μg/kg/h, severe liver dysfunction) for analysis and investigated regarding the correlation between endothelin-1 and the severity of liver failure, quantified by LiMAx test." (PMID 28542386, 2017).
meningioma (3 papers, 2022 to 2024). A generally slow growing tumor attached to the dura mater. "Meningiomas are closely associated with ossification and calcification, and the involvement of bone morphogenetic protein (BMP), insulin-like growth factor-1, endothelin-1, and osteoprotegerin has been investigated, but any function in meningioma cells is still unknown." (PMID 38446374, 2024).
metabolic acidosis (3 papers, 2018 to 2024). "Metabolic acidosis impairs kidney function by increasing levels of angiotensin II, aldosterone, and endothelin-1, leading to inflammation and fibrosis." (PMID 38899185, 2024).
multiple myeloma (3 papers, 2020 to 2024). "Aberrant activation of endothelin 1 axis is implied in several malignancies, including multiple myeloma." (PMID 38690165, 2024). "Polymorphisms in genes involved in nervous system function, NFATC1, NFATC4, and EDN1 were associated with CIPN in 646 myeloma patients treated with bortezomib, as were TCF4, DYNC1I1, and GJE1 in 139 myeloma patients treated with bortezmib." (PMID 35360655, 2022). "The endothelin-1 (ET-1) receptors were recently found to mediate pro-survival functions in multiple myeloma (MM) cells in response to autocrine ET-1." (PMID 33489901, 2020).